CD81 (CD81 molecule)
Diseases named in the same sentence as CD81 in open-access papers (continued):
Sharing a sentence is not in itself a finding about the gene and the disease.
eosinophilia (1 paper, 2020). "CD81 signaling causes several proinflammatory effects in the lungs, including bronchoconstriction and eosinophilia." (PMID 32258172, 2020).
eosinophilic esophagitis (1 paper, 2023). Eosinophilic esophagitis (EoE) is a chronic, allergic disease of the esophagus characterized clinically by symptoms of esophageal dysfunction (including vomiting, dysphagia, feeding disorders, food impaction and abdominal pain) which persist after treatment with proton pump inhibitors (PPIs). "Esophageal biopsies from 20 patients with eosinophilic esophagitis were stained for major basic protein, galectin-10, CD4, CD8, CD16, and CD81 and analyzed by immunofluorescence confocal microscopy before and after topical corticosteroid treatment." (PMID 36808213, 2023).
Fulminant hepatitis (1 paper, 2024). Acute hepatitis complicated by acute liver failure with hepatic encephalopathy occurring less than 8 weeks after the onset of jaundice. "First of all, HCV exerts a large genotype and subtype dependent heterogeneity and we only addressed CD81-modulation by the Jc1 viral genome, which is derived from an acute fulminant hepatitis." (PMID 38357447, 2024).
glomerulonephritis (1 paper, 2022). A renal disorder characterized by damage in the glomeruli. "HE and PAS staining of kidney sections also showed that CD81 mitigated the glomerulonephritis, mesangial matrix diffuse expansion and infiltration of lymphocytes." (PMID 35705919, 2022).
gout (1 paper, 2021). A condition characterized by painful swelling of the joints, which is caused by deposition of urate crystals. "CD81 levels were slightly, but not significantly, higher in gout patients (12.86 ± 4.788 × 1010 particles/mL, p > 0.05) than in OA patients (7.304 ± 2.324 × 1010 particles/mL)." (PMID 33435236, 2021).
head and neck squamous cell carcinoma (1 paper, 2022). A squamous cell carcinoma that arises from any of the following anatomic sites: lip and oral cavity, nasal cavity, paranasal sinuses, pharynx, larynx, and salivary glands. "Surprisingly, however, CD81 supports the growth and metastasis of various cancers and promotes the IFITM1-induced invasion of head and neck squamous cell carcinoma (HNSCC) cells." (PMID 36466909, 2022).
hemangioma (1 paper, 2021). A benign vascular lesion characterized by the formation of capillary-sized or cavernous vascular channels. "However, in contrast to normal endothelial cells, hemangioma cells lacked CD81 expression." (PMID 34638431, 2021).
humoral immune deficiency (1 paper, 2025). "Furthermore, a human case report of homozygous loss of function of CD81 was described; the major clinical manifestation was humoral immune deficiency, which was thought to be driven by the lack of CD81 expression in the B cells." (PMID 40677836, 2025).
Hypercalcemia (1 paper, 2018). An abnormally increased calcium concentration in the blood. "Neither decreased Klotho protein nor hypercalcemia was observed in the lung or epithelial cells of CD9/CD81 DKO mice; therefore, it is unlikely that the Klotho protein actively participates in the pathogenesis of DKO mice." (PMID 29572511, 2018).
joint disease (1 paper, 2023). "Although none have been described in joints or OA, CD81, calumenin, and TMED7 are promising candidates for further studies, focusing in particular on their potential ability to influence inflammation and degradation processes, to better understand their role in joint disease." (PMID 37443777, 2023).
keratoconus (1 paper, 2022). A degenerative, structural disorder of the eye, characterized by a cone-shaped protrusion of the cornea. "Among the proteins identified in exosomes, frequently accepted markers of nanovesicles such as CD81 and various Hsp70 species were found, including HSPA2 in both types of exosomes, HSP1B in healthy ones, and HSPA5 and HSPA6 in keratoconus." (PMID 36289615, 2022).
latent infections (1 paper, 2024). "In our research, contrasting with findings in HIV patients, we observed a significant increase in CD81 expression in γδ T cells of individuals with latent infections." (PMID 39329713, 2024).
lupus nephritis (1 paper, 2022). Glomerulonephritis in the context of systemic lupus erythematosus. "We conclude that CD39, CD81, CD326, and CD130 mark ASCs in kidneys of murine lupus nephritis." (PMID 35464469, 2022).
lupus-like syndrome (1 paper, 2022). "We surprisingly found that overexpression of CD81 ameliorated the lupus-like syndrome directly." (PMID 35705919, 2022).
malignant kidney tumors (1 paper, 2021). "In turn, in the 15 WT (out of 17 malignant kidney tumors analyzed) samples, neoplastic cells co-expressed CD9, CD81, and CD271 in the absence of HLADR and GD2, usually in the context of an EpCAM+ (13/15, 86%) phenotype." (PMID 34638431, 2021).
measles (1 paper, 2016). A highly contagious viral infection caused by the measles virus. "This is because breast-feeding is generally known to positively modulate response to vaccines (measles, mumps, rubella) through significant developmental changes in Th-1 pipeline response (CD81 T cells, natural killer cells, and mitogen-induced IFNg), as compared to formula-fed infants." (PMID 27656883, 2016).
medulloblastoma (1 paper, 2019). A malignant, invasive embryonal neoplasm arising from the cerebellum. "CD1d, CD38, and CD81 showed interesting expression profiles in the primary screen but have not been identified as markers of medulloblastoma and so they, along with CD117’s low expression in Ptch1 deleted cells, were not further investigated in this study." (PMID 30657775, 2019).
metastatic disease (1 paper, 2023). "The presence of EV was confirmed on western blot by the presence of EV-enriched proteins CD9, CD63, CD81 and TSG101 in SEC fractions 7 to 10 isolated from a healthy control and a patient with metastatic disease." (PMID 37046768, 2023).
monocytic leukemia (1 paper, 2019). "Additionally, CD81 was enriched in P100 but not in P200 fraction prepared from the CM of human monocytic leukemia cell line THP-1." (PMID 31416445, 2019).
muscle atrophy (1 paper, 2022). The loss of muscle tissue due to inactivity or disease. "Both knockdown of CD81 and blocking CD81 prevented the uptake of senescent BMSC-EVs by SCs, thus relieving harmful effects of senescent BMSC-EVs on muscle atrophy." (PMID 35846725, 2022).
neuroblastic tumor (1 paper, 2021). A group of nervous system tumors which display neuronal differentiation. "Thus, among neuroblastic tumors, i) CD90, GD2, CD9, and CD56 were the most discriminative between NBL and GNB, whereas ii) CD271, EpCAM, CD9, and CD81 discriminated NBL from PHEO." (PMID 34638431, 2021).
oral squamous cell carcinoma (1 paper, 2023). "The concentration of CD81 in exosomes in the oral fluids of patients with oral squamous cell carcinoma was 61.1±37 pg/ml, and that concentration of CD81 in the exosomes of oral fluids of healthy individuals was 201±79.5 pg/ml." (PMID 38059133, 2023).
osteoarthritis (1 paper, 2023). A noninflammatory degenerative joint disease occurring chiefly in older persons, characterized by degeneration of the articular cartilage, hypertrophy of bone at the margins and changes in the synovial membrane. "The specificity of the CD81 antibody was positively validated by IHC in CD81‐positive synovial tissue from osteoarthritis patients." (PMID 36321189, 2023).
pheochromocytoma (1 paper, 2021). "The only pheochromocytoma analyzed (n = 1) showed a distinct CD56++ CD57+ GD2++ CD271+ CD9+ CD81+ CD90het CD58+ phenotype, in the absence of expression of CD10, CD99, CD117, EpCAM, nuMyoD1, and numyogenin." (PMID 34638431, 2021).
preeclampsia (1 paper, 2023). Preeclampsia is a hypertensive disorder of pregnancy that is characterized by new-onset hypertension with proteinuria presenting after 20 weeks of gestation, and depending on mild or severe forms may initially present with severe headache, visual disturbances, and hyperreflexia. "Expanding our prior research on placental cluster of differentiation 81 (CD81), this study explores the interaction of renal CD81 with sodium transporters in preeclampsia (PE)." (PMID 36961378, 2023).
rectum tumors (1 paper, 2021). "Tumor infiltrating lymphocytes in CRC differs by primary tumor site; high CD81 cell density is associated with favorable prognostic factor for patients with right-sided colon tumors while CD31 cell density is a favorable prognostic factor for right colon and rectum tumors." (PMID 33652647, 2021).
schwannoma (1 paper, 2025). A benign, usually encapsulated slow growing tumor composed of Schwann cells. "Small extracellular vesicles (sEVs) derived from NF2-associated schwannomas (NF2-EVs) express CD9 and CD81, with a size distribution ranging from 50 to 200 nm." (PMID 41149489, 2025).
seminoma (1 paper, 2019). A radiosensitive malignant germ cell tumor found in the testis (especially undescended), and extragonadal sites (anterior mediastinum and pineal gland). "All investigated seminomas showed a strong membranous expression of CD81 in tumor cells (arrow)." (PMID 31565104, 2019). "However, the high expression of CD81 on TCam-2 and seminoma samples is interesting given the induction of nonseminoma-like phenotype by TGF beta signaling." (PMID 31565104, 2019).
soft tissue sarcoma (1 paper, 2021). A malignant neoplasm arising from muscle tissue, adipose tissue, blood vessels, fibrous tissue, or other supportive tissues excluding the bones. "Among soft tissue sarcomas, CD271, GD2, CD9, and CD90 allowed for the differential diagnosis between EES and RMS, and the CD9, CD81, CD99, and CD271 markers distinguished between OS and CDS." (PMID 34638431, 2021).
squamous carcinoma (1 paper, 2008). "Testing of other cell lines indicated that such a CD81 partner is probably also present in other cell lines such as A431, a squamous carcinoma cell line." (PMID 18382656, 2008). "We also analysed SR-BI and CLDN-1 expression in the same cell lines, and the lack of interaction between CD81 and E1E2 glycoproteins cannot be correlated with the absence of these molecules (see squamous carcinoma, A431)." (PMID 18382656, 2008).
squamous cervical cancer (1 paper, 2024). "In patients with squamous cervical cancer, APOA1 overexpression can reduce the sensitivity of cervical squamous cells to carboplatin by regulating the expression of STAT1, CD81, C3, and TOP2A." (PMID 38212711, 2024).
thrombosis (1 paper, 2021). "Of note, the expression of tetraspanins, namely CD81, CD63, and CD9, and the number/size of the isolated EVs were not significantly different between PV patients with or without thrombosis history (data not shown)." (PMID 34638452, 2021).
tumor (188 papers, 2009 to 2026). "In summary, our study indicated that CD81 was a potential pathogenic target for OC, and its regulation of the crosstalk between cancer cells and TAMs was crucial in tumours." (PMID 40604335, 2025). "CD81 is also an anticancer target implicated in cancer cell proliferation and mobility, and in tumor metastasis." (PMID 37046846, 2023). "The expression levels of BCL-2 (P < 0.01), clCasp3 (P = 0.04), Ki-67 (P = 0.04) and CD81 which has been associated with chemoresistant MM tumor cells (P < 0.01), were significantly higher in RRMM than in NDMM samples consistent with a more aggressive disease." (PMID 37217482, 2023). "As in prior studies, high CD81 expression on tumor PCs was associated with inferior PFS in our patients with MM." (PMID 36752202, 2023). "Following the ISEV2018 guidelines, the EV characterization showed the presence of the EV-specific markers: CD9 molecule (CD9), CD81 molecule (CD81), and Tumor Susceptibility 101 (TSG101) in our serum." (PMID 35659238, 2022). "CD81 is associated with patient survival and enriched in circulating tumor cells (CTCs) promoting tumor cell aggregation." (PMID 36193887, 2022). "Increased expression of CD9 and CD81 was detected in multiple tumors and associated with increased tumor cell motility and improved tumor growth." (PMID 36203458, 2022). "CD81 is coexpressed along with CD44 in human circulating tumor cells (CTCs) and enriched in clustered CTCs that promote cancer stemness and metastasis, supporting the clinical significance of CD81 in association with patient outcomes." (PMID 36193887, 2022). "The tool is demonstrated by detection of EVs isolated from cell culture supernatants and various body fluids using characteristic biomarkers, CD9 and CD81, and a tumor-associated marker—epithelial cell adhesion molecules." (PMID 35564289, 2022). "We successfully tested the tool for quantification of EVs harboring common EV markers, namely, CD9 and CD81, and a tumor-associated biomarker EpCAM." (PMID 35564289, 2022). "CD9, CD63, and CD81, in conjunction with other tetraspanins, promote (in association with exosomes) cancer cell motility, invasion, metastasis, tumor initiation, promotion, progression, and angiogenesis." (PMID 33669943, 2021). "We detected tetraspanin proteins (CD9, CD63, CD81), Alix and tumor susceptibility gene-101 (TSG101) of exosomal markers from rotenone treated CSCs." (PMID 25682864, 2015). "Conversely, compared to low CD81 expression, high CD81 expression was associated with a 0.650-fold decreased risk for tumor recurrence (p < 0.001) and a 0.630-fold decreased risk for progression (p = 0.005)." (PMID 25915404, 2015). "CREBBP and CD81 alterations were associated with a 2.029-fold (p = 0.048) and 0.727-fold (p = 0.018) increased risk for tumor recurrence, respectively." (PMID 25915404, 2015). "As a proof of concept we have confirmed expression of 7 proteins; two proteins confirm the origin of the hMSCs EVs (CD90 and CD81) and five known proteins associated with tumor proliferation and anti-metastasis." (PMID 25669974, 2015). "These conclusions are supported by our ex vivo studies demonstrating an association between histological tumour grade and CD81 expression." (PMID 24662676, 2014). "Matrix metalloproteinases (MMP) play a significant role in tumour invasion and metastasis and CD81 has been reported to associate with MT1-MMP." (PMID 24662676, 2014). "The tetraspanin superfamily proteins (TM4SF) mainly CD9, CD63, CD82, CD151 and CD81 have been implicated in cell migration, proliferation and tumor cell metastasis." (PMID 23128478, 2013). "It was demonstrated that the diminishment of CD81 in regulatory T cells and innate myeloid-derived suppressor cells interfered their recruitment to tumor microenvironment and thus limited immune escape and metastatic dissemination of tumor cells in CD81-deficient mice." (PMID 33919192, 2021).
tumor (continued). "CD81 belongs to the Tetraspanins, a large family of transmembrane proteins ubiquitously expressed and implicated in cell proliferation, differentiation, and tumor invasion." (PMID 33671568, 2021). "CD81 down-expression was mainly associated with tumor location, treatment, and death." (PMID 34065085, 2021). "Further ImageStream analysis revealed the expression of epithelial cell adhesion molecule (EpCAM) and exosome specific surface markers, including CD9, CD63, tumor susceptibility gene 101 (TSG-101), and CD81 confirming the tumor cell-derived vesicles as exosomes." (PMID 32456301, 2020). "Our observation that increased CD81 expression associates with tumour grade may be indicative of increased MT1-MMP expression in poorly differentiated tumours." (PMID 24662676, 2014). "Tumor-associated macrophages constitute 30% of the tumor mass in glioblastoma, favoring the transition to the M2 immunosuppressive phenotype which inhibits cluster of differentiation (CD) 41 and CD81 T-cell functions and induces regulatory T-cell differentiation." (PMID 36980182, 2023). "Downregulation of CCND2, a protein known to cause growth arrest in the G1 cell cycle phase, and CD81, a protein relevant for membrane organization, protein trafficking, cellular fusion and cell-cell interactions, contributes to a decreased proliferation, tumor progression, migration, and invasion." (PMID 33690729, 2021). "CLDN1-overexpressing SW620 cells and a xenograft tumor model were cotreated with the anti-CD81 monoclonal antibody (mAb) 5A6 to investigate the role of the CLDN1/CD81 axis in CRC tumor growth." (PMID 42232600, 2026). "The tetraspanin CD81 would act as a tumor suppressor in some cancers or as a tumor-promoting factor in others." (PMID 41008614, 2025). "For in vitro experiments, we used tumour conditional medium (TCM) from ID8 cells (NC or sh‐CD81 ID8‐TCM) to induce Tim4+ RAW264.7 cells (tumour‐conditioned RAW264.7 cells), and the overexpression of Tim4 protein has been verified after treatment." (PMID 40604335, 2025). "The number of tumour nodules in the abdominal organs (liver, spleen and kidney) was also decreased by down‐regulating CD81." (PMID 40604335, 2025). "We further analysed the protein expression of CD81 in tumour adjacent normal tissues and OC tissues from human samples through immunohistochemistry." (PMID 40604335, 2025). "We then found that the proportion and number of Tim4+ TAMs (CD45+CD11b+F4/80+Tim4+) were both decreased when CD81 expression of OC cells was knocked down in the peritoneal metastasis murine tumour model, which were in accordance with the remission of tumours." (PMID 40604335, 2025). "We found that CD81 expression was significantly elevated in tumour tissues from OC patients with poor prognosis, and it directly promoted proliferation, and migration of OC cells." (PMID 40604335, 2025). "Through fluorescence imaging, measuring size and weighing, we found that CD81 knock‐down absolutely inhibited tumour growth." (PMID 40604335, 2025). "Mice in the sh‐CD81 group had lighter body weight and smaller abdominal circumference than the NC group during the terminal stage of the metastasis tumour model, indicating lower production of ascites in the sh‐CD81 group." (PMID 40604335, 2025). "In vivo imaging exhibited that knock‐down of CD81 expression significantly relieved the tumour burden of advanced diffuse OC inside the abdominal cavity, indicating deceleration of cancer growth and metastasis." (PMID 40604335, 2025). "A deeper analysis revealed upregulation of genes involved in tumor suppression (Clca2, Spink5, Igfbp6, Nptx1, Bex4, Gadd45g, Yipf5), immune regulation (IL6ra, Ccl6, Cd81, Cd244a, Cd151, and Gata4), apoptosis, and pyroptosis (Ddit3, Rgs6, and Gsdmsc2/3/4)." (PMID 39946195, 2025). "For instance, knockout of CD81 in the osteosarcoma cell line 143B reduced tumour formation and lung metastasis in mice." (PMID 40604335, 2025).